TLR2 (toll like receptor 2)
Diseases named in the same sentence as TLR2 in open-access papers (continued):
Sharing a sentence is not in itself a finding about the gene and the disease.
tuberculosis (continued). "The table summarizes the mean percentages of inflammatory cells expressing TLR1, TLR2, TLR4, TLR7, and TLR9 in LNs from patients with AOSD, tuberculosis (Tb) lymphadenitis, T cell lymphoma, histiocytic necrotizing lymphadenitis (HNL), and reactive LNs." (PMID 35715478, 2022). "Mycobacterial components are known TLR2 and TLR4 agonists, and MyD88 dependent signaling is necessary to prevent lethality in response to infection to tuberculosis." (PMID 35921962, 2022). "TLR-2 and TLR-4 have been considered important in the development of the inflammatory response and pathology in several infectious diseases, such as tuberculosis, malaria, and toxoplasmosis." (PMID 33194814, 2020). "There is evidence that TLR10, a TLR2 signaling modulator, may be involved in progression of tuberculosis (TB)." (PMID 29527210, 2018). "TLR2 and TLR4 play a central role in the immune response against tuberculosis by secreting proinflammatory cytokines and activating other molecular mechanisms, such as autophagy, which can limit intracellular bacterial growth." (PMID 26347897, 2015). "In this study, we evaluated the gene and cell surface expression of TLR2 and TLR4 in pulmonary tuberculosis patients during anti-tuberculosis treatment." (PMID 24558401, 2014). "Among the TLR family, TLR2, TLR4, and TLR9 and their adaptor molecule MyD88 play the most prominent roles in the initiation of the immune response against tuberculosis." (PMID 21603213, 2011). "Considering the fact that India is home to a third of the global cases of tuberculosis, we hypothesized that these SNPs in the TLR2 gene could contribute to the high burden of TB among Indian patients." (PMID 19686607, 2009). "Using a trend test, we found that expression of Toll-like receptor 2 was greater from absence of infection to latent infection and from latent infection to active tuberculosis." (PMID 29104936, 2017). "We conclude that the level of TLR2 (but not TLR4) changes with tuberculosis infection state but not with tuberculosis disease severity." (PMID 29104936, 2017). "Our study evaluated the mRNA and cell surface expression of TLR2 and TLR4; iNOS expression; and the production and expression of IL-12, IFN-γ, TNF-α, IL-17, IL-10 and TGF-β in pulmonary tuberculosis patients during anti-tuberculosis treatment." (PMID 24558401, 2014). "In support of this hypothesis, the TLRs are upregulated as a group in both melioidosis (TLR1, TLR2, TLR4, TLR5, TLR6, TLR8 and TLR10) and tuberculosis (TLR2, TLR4, TLR5, TLR6, TLR7, TLR8)." (PMID 23383015, 2013). "Others study reported increased TLR2/TLR4 mRNA gene expression in latent tuberculosis infection (LTBI) than in non infected, and increased in active TB than LTBI or healthy individuals." (PMID 35638072, 2022). "Our objective was to evaluate the mRNA and cell surface expression of TLR2 and TLR4; inducible nitric oxide synthase (iNOS) expression; and cytokine Th1, Th2 and Th17 profiles in pulmonary tuberculosis patients at different time points of anti-tuberculosis treatment." (PMID 24558401, 2014). "The expression of TLR-2 is already known to be induced on activated CD4+ T cells and is constitutively expressed on effector memory CD4+ T cell populations, in addition to effector cells derived from patients with persistent bacterial infections and tuberculosis." (PMID 24896098, 2014). "TLR polymorphism with a significant association with pulmonary tuberculosis was present in TLR1 rs5743572 in intron, TLR2 rs3804100 in exon, and TLR6 rs5743808 in exon and among MDR-TB isolates from patients with pulmonary MDR-TB of a severe and moderate/mild degree." (PMID 36611413, 2022). "In the subgroup analysis by sample type, TLR2 Arg753Gln polymorphism is associated with high pulmonary tuberculosis (PTB) risks, but not with EPTB or TB." (PMID 30733958, 2019).
tuberculosis (continued). "We evaluated macrophage expression of VDR, TLR2, cathelicidin, and TNF-α, and production of IL-1β in HIV-seronegative persons with previous EPTB, previous pulmonary TB, latent M. tuberculosis infection, and uninfected TB contacts." (PMID 31039752, 2019). "In pulmonary leucocytes obtained from patients with tuberculosis, NOD2 mRNA expression correlated with TLR2 (p = 0.02) and TLR4 (p = 0.01) but not with TLR6 mRNA expression (p = 0.17)." (PMID 17705850, 2007). "An increase in TLR2 expression on CD14low and CD14high cells was observed in the peripheral blood of HIV-coinfected LTBI individuals compared to healthy HIV-negative, LTBI-positive individuals and active tuberculosis patients with or without HIV infection." (PMID 39339847, 2024). "In this regard, a directly proportional expression between CD64, TLR2, and TLR4 has been described in monocytes differentiated into macrophages from peripheral blood and neutrophils from tuberculosis patients, but not in vitro macrophages differentiated to a pro-inflammatory profile." (PMID 36077408, 2022). "In a recent study, an increased expression of TLR-1, TLR-2, TLR-4 and TLR-6 has been reported at the mRNA level in peripheral blood mononuclear cells, but not in broncho-alveolar lavage cells from patients with tuberculosis compared to healthy controls." (PMID 20718957, 2010).
diabetes (80 papers, 2011 to 2026). "A systematic review also concluded that diabetes is associated with elevated TLR-2 mRNA and protein levels in peripheral blood, as well as increased receptor activation." (PMID 40746553, 2025). "The results demonstrate that the severity of renal fibrosis is positively associated with the activation of HMGB1/TLR2/4 signaling in diabetes." (PMID 36448056, 2022). "Recently, it has been proposed the association of a common deletion affecting toll-like receptor 2 promoter (-196 to -177) to type 2 diabetes mellitus risk." (PMID 32347052, 2020). "It is shown that TLR2 senses β-cell death and contributes to diabetes, and concluded that the deficiency of TLR2 decrease the diabetes-induced inflammation." (PMID 31752797, 2019). "TLR2 has been implicated in the pathogenesis of systemic lupus erythematosus, diabetes, Alzheimer’s disease." (PMID 26226614, 2015). "Recent experimental studies support this concept as TLR2 or TLR4 deficiency attenuated the pro-inflammatory state generated in wild-type mice with STZ-induced diabetes." (PMID 24842252, 2014). "Notably, the inhibition of the TLR2/4 signaling pathway decreases the levels of such inflammatory cytokines in diabetic animals, indicating a causative relationship between TLR2/4 and inflammation in diabetes." (PMID 34401982, 2021). "Thus, studies aiming to block TLR2, as a therapeutic target to prevent complications caused by Diabetes mellitus, will be important." (PMID 28164040, 2017). "The close association between TLR2 activation and IL-1β secretion and their influence on arrhythmogenesis indicates that TLR2 and IL-1β are part of an inflammatory pathway that has a major role in the pathogenesis of diabetes-associated electric dysfunction of the heart." (PMID 27882934, 2016). "The hallmark of diabetes is hyperglycemia and several studies showed that hyperglycemia could cause increased TLR2/4 expression and activity in different cell types." (PMID 26312071, 2015). "By combining immunometabolic and neurodegenerative pathways, this review highlights TLR2 as a promising target for preventing or reducing diabetes-related cognitive decline neurodegeneration." (PMID 41947971, 2026). "Using LASSO feature selection followed by multivariable logistic regression, a diagnostic nomogram was developed incorporating TLR2, IL-6, TNF-α, ESR, age, and diabetes duration." (PMID 41788768, 2026). "Conversely, in a murine model of induced diabetes, reduced TLR-2 expression was reported in the brain, kidney, and liver." (PMID 40746553, 2025). "Knockout of TLR2 has been shown to prevent impaired cerebral blood flow in early diabetes and VCI by counteracting overperfusion in long-term diabetes." (PMID 38736878, 2024). "Diabetes mellitus positively influenced TLR-2 expression on macrophages but adversely affected IL-6 and TNF-α levels." (PMID 39456722, 2024). "TLR2 knockout protected the NOD mice from diabetes, but the protection was reversed in the germ-free setting, indicating that TLR2 interaction with the microbiota promotes diabetes." (PMID 36059452, 2022). "Deleting MyD88 or TLR2/4 from bone marrow-derived immune cells significantly reduces diabetes-induced pathological changes in the retina such as leucostasis, vascular permeability, superoxide generation and intercellular adhesion molecule 1 (ICAM-1)." (PMID 38983565, 2022). "In a mouse model of diabetes mellitus, they showed that hyperglycemia activates the toll-like receptor 2 (TLR2) and the NLRP3 inflammasome in recruited cardiac MHC-IIhigh macrophages which in turn causes release of IL-1β." (PMID 35812333, 2022). "Diabetes-induced changes in cerebral blood flow and cognitive deficits were prevented when TLR2 was knocked out." (PMID 35873459, 2022). "Increased expression of TLR2 and TLR4 has been found in patients with T2D, highlighting their associations with the pathogenesis of diabetes." (PMID 36552771, 2022).
diabetes (continued). "The number (p = 0.040) of CD4+ TLR2+ T cells in children with long-term type 1 diabetes mellitus was higher than in the control group." (PMID 34830017, 2021). "For instance, in diabetes, propolis helped increasing TLR-2 and TLR-4, thus activating the B and T function, improving the lipid profile, reducing the ROS and modulating the HbA1C and FSG glycemic factors." (PMID 35047540, 2021). "It was shown that the percentage (p = 0.018) and the number (p = 0.003) of lymphocytes with the CD4+ TLR2+ phenotype in the peripheral blood of patients with type 1 diabetes mellitus were higher than in the control group." (PMID 34830017, 2021). "The percentage (p = 0.010) and number (p = 0.002) of CD4+ TLR2+ T cells in patients with newly diagnosed type 1 diabetes mellitus were higher compared to the control group." (PMID 34830017, 2021). "TLR2, MyD88, and proinflammatory cytokines in leukocytes of patients with type 1 diabetes mellitus suggests that the inflammatory process is mediated by TLR2." (PMID 32933213, 2020). "The effects of Pae on the kidneys of mice with streptozotocin-induced type 1 diabetes mellitus was evaluated by using TLR2 knockout mice (TLR2-/-)." (PMID 30804784, 2019). "Blockade of TLR2 in intact aortas using an anti-TLR2 antibody attenuates an increase in vascular contraction in rats with streptozotocin-induced diabetes." (PMID 31582899, 2019). "TLR2 is critical in the pathogenesis of IR, inflammation and diabetes in both clinics and experiments." (PMID 31752797, 2019). "It is most likely that the main mechanisms of anti-diabetes involve suppressing TLR2 signalling pathway, stimulating the insulin signalling pathway and the interactions of the two through TNF-α based upon the bioactive compounds identified from WEM." (PMID 31752797, 2019). "In the monocytes of type 1 and type 2 diabetes patients, levels of TLR2, TLR4, and other TLR-signaling components (e.g., MyoD88 and NF-κB) were increased." (PMID 28824448, 2017). "In a model of diabetes, TLR2−/− mice showed a decrease in NF-κB and cytokine release and an increase in wound closure." (PMID 29230082, 2017). "Our findings, together with those of these authors, suggest that in a diabetes mellitus environment, TLR2 acts to promote a pro-inflammatory response." (PMID 28164040, 2017). "Deletion of TLR2/4 or IL-1βr from marrow-derived cells partially inhibited the diabetes-induced increase in leukostasis (by 56% or 75% (both P<0.05))." (PMID 23874797, 2013). "We found that diabetic, but not normal retinas, were stimulated by Pam3CysK, which activates the TLR2/MyD88 pathway, and supports the concept that this pathway is up-regulated in the retina in diabetes." (PMID 23874797, 2013). "Overexpression of TOLLIP in diabetes was yet another possible mechanism for inhibition of TLR2- and TLR4-mediated NFκB activation." (PMID 23149823, 2013). "The ability of TLR2 polymorphisms to influence the intensity of the inflammatory response is particularly important in diseases characterized by chronic inflammation, such as chronic obstructive pulmonary disease (COPD), rheumatoid arthritis, and diabetes." (PMID 41295183, 2025). "In addition, TLR2 and TLR4 activation can lead to endothelial dysfunction and vascular complications associated with diabetes." (PMID 40076851, 2025). "In patients with diabetes, TLR2, TLR4, and TLR7 expression levels are four to six times higher." (PMID 38685971, 2024). "The activation of TLR2 and TLR4 receptors could underlie the pathophysiological mechanisms of many human diseases including bronchial asthma (BA), type 2 diabetes mellitus (T2DM), obesity, metabolic syndrome, and autoimmune diseases." (PMID 36836906, 2023). "Our data thus suggest that TLR2 activation and/or AGEs formation in diabetes may be deleterious for wound healing, in part via downregulation of AQP3 protein in this condition." (PMID 36674890, 2023).
diabetes (continued). "In conclusion, our study suggests that glycemic fluctuation in diabetes causes more damage in peri-implantitis compared with uncontrolled hyperglycemia, through regulating TLR2/4-IRAK1-TRAF6 pathway but not NAMPT/SIRT1 signaling." (PMID 34401982, 2021). "Furthermore, CD163, a predictor of increased risk of developing T2D and Toll-like Receptor 2 (TLR2), a receptor involved in insulin resistance, inflammation, and diabetes, were found to be also elevated in N363S carriers in the presence of Dex." (PMID 34681832, 2021). "High TLR2 expression was also observed in the glomeruli and renal tubules of people with diabetes." (PMID 32933213, 2020). "TLR2 is also believed to play a role in wound healing in diabetes." (PMID 29230082, 2017). "The authors found that deficiency of TLR4 but not of TLR2 alleviates several diabetes-induced changes, including albuminuria, tubulointerstitial fibrosis, kidney inflammation and tubular apoptosis." (PMID 26398934, 2015). "A deficiency of TLR4 but not of TLR2 alleviated albuminuria, tubulointerstitial fibrosis and inflammation induced by diabetes." (PMID 26398934, 2015). "The authors found that both TLR2 and TLR4 expression and activity were increased in the monocytes of patients with MetS and could contribute to an increased risk for diabetes and CVD." (PMID 25329057, 2014). "The TLR2 induction has been reported in both diabetic patients and experimentally induced diabetes." (PMID 24835775, 2014). "In line with this, in a streptozotocin (STZ)-induced diabetes mouse model, knockout of TLR2 improved wound healing and reduced oxidative stress, MyD88 signaling, NF-κB activation, and cytokine secretion, suggesting that sustained TLR2 expression and activation may be detrimental to diabetic wounds." (PMID 33233704, 2020). "However, inhibition of TLR2 or TLR4 in diabetes exhibited reduced inflammatory responses, indicating that TLR2 or TLR4 might mediate HMGB-1-induced inflammation in DN." (PMID 27847406, 2016). "Thus, we propose a mechanism that, in the early stage of diabetes, a leakage of albumin into the renal tubules upregulates TLR2 and TLR4 and induces HSP70 release and TLR4 activation, leading to a more severe injury and a stronger inflammatory response in the tubule and interstitium." (PMID 26398934, 2015). "Increased expression of TLR2 and 4 has been found in monocytes from patients with type 1 and 2 diabetes mellitus, suggesting TLR2 and 4 may play an important role in the inflammatory milieu which characterizes diabetes." (PMID 24842252, 2014). "Leukocytes from animals deficient in TLR2/4 caused essentially none of the expected diabetes-induced increase in endothelial death, suggesting that pathways regulated by TLR-2 or -4 (or both) are largely responsible for the leukocyte-mediated death of endothelial cells." (PMID 23874797, 2013). "Similarly, under specific pathogen-free conditions, TLR2 deficiency reduces diabetes incidence in non-obese diabetic (NOD) mice; however, this protective effect is abrogated under germ-free conditions, highlighting a microbiota-dependent modulation of TLR2-mediated diabetogenicity." (PMID 40969771, 2025). "Furthermore, an in silico study suggests that the combination may interact with TLR2 and DECTIN1 receptors, and increase the expression of Tlr2 and Clec7 to directly modulate inflammatory gene expression in macrophages and upregulate the expression of their receptors during diabetes." (PMID 41009577, 2025). "Further, TLR-2, TLR-4, TLR-5, TLR-9, and others play a critical role in the pathogenesis of IBD, and TLR-2, TLR-1, TLR-4, TLR-6, and TLR-7 contribute to diabetes." (PMID 39328924, 2024). "Here, we show in vitro that DOPG inhibits TLR2 activation induced in response to HSPB4, as well as DAMPs that are elevated in diabetes, a disease that also slows corneal wound healing." (PMID 36982926, 2023).